BBOX1 (gamma-butyrobetaine hydroxylase 1)
Description:
Catalyzes the formation of L-carnitine from gamma-butyrobetaine.
Synonyms: Gamma-BBH; BBH; BBOX; G-BBH
Tractability: Small molecule: a structure with a bound ligand is known; a high-quality ligand is known. PROTAC: its protein half-life has been measured; a small molecule that binds it is known.
Target class: Enzyme; Oxidoreductase
Gene: Protein-coding gene on chromosome 11 (27,040,698 to 27,127,810, forward strand). Ensembl gene ENSG00000129151.
Subcellular location: Cytoplasm
Subcellular location (Human Protein Atlas): Vesicles; Actin filaments
Pathways (Reactome):
Metabolism: Carnitine synthesis
Gene Ontology:
Molecular function: gamma-butyrobetaine dioxygenase activity; identical protein binding; protein binding; zinc ion binding; iron ion binding; oxidoreductase activity
Biological process: carnitine biosynthetic process
Cellular component: extracellular exosome; cytosol; mitochondrion; cytoplasm
Genetic constraint (gnomAD): Loss-of-function variants: 27 observed, 37.87 expected, observed/expected ratio (o/e) 0.71, 90% interval 0.52 to 0.98. The upper end of that interval is the gene's LOEUF score, 0.98, which puts it in group 4 of 6, group 1 being the genes least tolerant of losing a copy. Missense variants: 424 observed, 435.13 expected, observed/expected ratio (o/e) 0.97, 90% interval 0.9 to 1.06. Synonymous variants: 155 observed, 147.42 expected, observed/expected ratio (o/e) 1.05, 90% interval 0.92 to 1.2.
Homologues: Orthologues: chimpanzee BBOX1 (100% identical), macaque BBOX1 (97% identical), rabbit BBOX1 (91% identical), mouse Bbox1 (89% identical), guinea pig BBOX1 (88% identical), rat Bbox1 (88% identical), pig BBOX1 (88% identical), dog BBOX1 (71% identical), tropical clawed frog bbox1 (62% identical), zebrafish bbox1 (43% identical), Drosophila melanogaster CG5321 (37% identical), Drosophila melanogaster CG10814 (35% identical), and 2 more. Paralogues in human: TMLHE (27% identical).
Diseases named in the same sentence as BBOX1 in open-access papers:
BBOX1 is named in the same sentence as 40 diseases in open-access papers, as found by Europe PMC text mining. Sharing a sentence is not in itself a finding about the gene and the disease. The quoted sentences say what the papers report.
triple-negative breast carcinoma (3 papers, 2022 to 2023). An invasive breast carcinoma which is negative for expression of estrogen receptor (ER), progesterone receptor (PR), and human epidermal growth factor receptor 2 (HER2). "Intriguingly, BBOX1’s upregulation is not limited to PDAC but extends to triple-negative breast cancer, a disease that is also known to be intricately linked to MYC activation." (PMID 37980563, 2023). "BBOX1 inhibitors can restrain the progression of triple-negative breast cancer." (PMID 36199579, 2022).
clear cell renal cell carcinoma (2 papers, 2023). "The purpose of this study was to analyze the prognosis, immune response, and genetic alterations associated with low BBOX1 expression in patients with clear cell renal cell carcinoma (RCC)." (PMID 36864013, 2023). "Moreover, studies have demonstrated that a decrease in the expression of BBOX1 antisense RNA 1 (BBOX1-AS1) corresponds to diminished cellular viability and proliferation, and low BBOX1 expression serves as a prognostic biomarker for clear cell renal cell carcinoma (RCC)." (PMID 37808522, 2023).
Obesity (2 papers, 2012 to 2025). Accumulation of substantial excess body fat. "In summary, BBOX1, SSTR1, MMP7, and LACC1 are identified as diagnostic markers of obesity and NAFLD." (PMID 39619480, 2025). "BBOX1, SSTR1, MMP7, and LACC1 emerged as common predictors for obesity and NAFLD through animal experimentation and predictive model analysis." (PMID 39619480, 2025). "Obesity and NAFLD share a molecular mechanism with BBOX1, SSTR1, MMP7, and LACC1, which play crucial roles in disease development and can serve as common predictors." (PMID 39619480, 2025). "Since endurance exercise causes activation of PPARα, these data suggest that endurance exercise was able to restore at least in part the obesity-induced disruption of PPARα function and thereby contributed to the elevated gene expression of OCTN2, ALDH9A1, and BBOX1." (PMID 23150726, 2012).
ovarian carcinoma (2 papers, 2023 to 2025). A malignant neoplasm originating from the surface ovarian epithelium. "We compared BBOX1 expression levels across human cancer cell lines and selected two ovarian cancer cell lines with high levels of BBOX1 mRNA: OVCAR-3 and Kuramochi." (PMID 41075794, 2025). "A study utilizing ovarian cancer cells demonstrated that BBOX1 silencing is related to anti‐apoptotic and pro‐proliferative properties." (PMID 36864013, 2023).
adenocarcinoma of the breast (1 paper, 2017). "CELF1 has been found involved in previous fusions with five different partners: with MTCH2 and MYOM1 in SCC and adenocarcinoma of the lung, respectively; with LUZP2 and ARFGAP2 in adenocarcinoma of the breast; and with BBOX1 in grade I-II astrocytoma of the brain." (PMID 28186972, 2017).
colorectal cancer (1 paper, 2023). A primary or metastatic malignant neoplasm that affects the colon or rectum. "However, another study showed that high BBOX1 expression is associated with a high risk of colorectal cancer." (PMID 36864013, 2023).
glioma (1 paper, 2019). A benign or malignant brain and spinal cord tumor that arises from glial cells (astrocytes, oligodendrocytes, ependymal cells). "In addition to D-2HG production, because 2OG is maintained at very low levels in clinical gliomas with IDH mutation, BBOX 1 and BBOX 2 activities might be strongly inhibited." (PMID 31278288, 2019).
glomerulonephritis (1 paper, 2019). A renal disorder characterized by damage in the glomeruli. "We found that tubular BBOX1 mRNA expression is quite stable in hypertensive nephropathy and various types of glomerulonephritis, suggesting that elevated uBBOX1 may also act as an indicator of tubular injury in these kidney diseases." (PMID 30819181, 2019).
kidney cancer (1 paper, 2023). Primary or metastatic malignant neoplasm involving the kidney. "We analyzed clinicopathologic factors, survival rates, immune profiles, and gene sets according to BBOX1 expression in a total of 857 patients with kidney cancer from the Hanyang University Hospital cohort (247 cases) and The Cancer Genome Atlas (610 cases)." (PMID 36864013, 2023).
psoriasis (1 paper, 2023). An autoimmune condition characterized by red, well-delineated plaques with silvery scales that are usually on the extensor surfaces and scalp. "We also found that BBOX1 was downregulated in skin lesions of patients with psoriasis, based on the analysis of a public database, and BBOX1 was negatively related to CD147 expression in psoriasis skin lesions, indicating that CD147 has an essential role in carnitine biosynthesis in psoriasis." (PMID 37303600, 2023). "BBOX1 was negatively related to CD147 expression in psoriasis skin lesions, indicating that CD147 has an essential role in carnitine biosynthesis in psoriasis." (PMID 37303600, 2023).
renal carcinoma (1 paper, 2023). A carcinoma arising from the epithelium of the renal parenchyma or the renal pelvis. "In the human protein atlas project, low BBOX1 expression correlated to unfavorable prognosis in renal cancer." (PMID 36864013, 2023). "Midostaurin, BAY‐61‐3606, GSK690693, and linifanib effectively inhibited the growth of renal cancer cells with low BBOX1 expression." (PMID 36864013, 2023). "We analyzed the relative influence of BBOX1 on survival using machine learning and investigated drugs that can inhibit renal cancer cells with low BBOX1 expression." (PMID 36864013, 2023).
schizophrenia (1 paper, 2019). A major psychotic disorder characterized by abnormalities in the perception or expression of reality. "The authors also did a case control study on 284 subjects with schizophrenia and 409 healthy controls and found that BBOX 1 polymorphisms could be associated with increased schizophrenia susceptibility in the Korean population." (PMID 31500110, 2019).
scrapie (1 paper, 2014). A fatal disease of the nervous system in sheep and goats, characterized by pruritus, debility, and locomotor incoordination. "Our results confirm the altered expression of BBOX1, a gene implicated in the systemic response of the organism to prion-induced oxidative stress, in scrapie infected animals." (PMID 24450868, 2014). "Our results demonstrate upregulation of BBOX1 in both clinical and preclinical stages of scrapie in the LRS, perhaps reflecting an increase in the levels of antioxidant molecules (L-carnitine and acetyl-L-carnitine) in response to the damage induced by the prion." (PMID 24450868, 2014).
serous ovarian cancer (1 paper, 2025). "BBOX1 expression is upregulated in several cancers, including high-grade serous ovarian cancer." (PMID 41075794, 2025).
steatosis (1 paper, 2025). Increased lipid within the cytoplasm of cells. "The roles of manipulating hepatocyte TGR5 and TRIM21, as well as overexpressing BBOX1 and other therapeutic targets, in the progression from steatosis to MASH were explored in this study, considering both “therapeutic” and “prevention” approaches." (PMID 40344326, 2025). "In the steatosis model, SBI‐115 treatment did not significantly alter TGR5 expression, BBOX1 protein level, or hepatocyte cell death rate (as indicated by RIP3 positivity)." (PMID 40344326, 2025).
cancer (7 papers, 2018 to 2025). A tumor composed of atypical neoplastic, often pleomorphic cells that invade other tissues. "In pathway network analyses, BBOX1 was linked to ‘lysine degradation’, ‘monocarboxylic acid catabolic process’, ‘T‐cell antigen receptor signaling pathway’, ‘cancer immunotherapy by PD‐1 blockades’, and ‘antigen processing and presentation’." (PMID 36864013, 2023). "In contrast, BBOX1 was indirectly linked to the monocarboxylic acid catabolic process T‐cell antigen receptor signaling pathway, antigen processing and presentation, and cancer immunotherapy by PD‐1 blockade." (PMID 36864013, 2023). "The upregulated genes, including WNT11, HAPLN1, FGF10, BBOX1, CXADR, NDP, and EREG are associated with tumor proliferation, migration, and cancer stemness." (PMID 35954313, 2022). "Through meta-analysis of microarray data across 13 different types of cancers, BBOX1 has been proposed to have an important role in cancer development." (PMID 30008265, 2018). "Conversely, cancer exosomes triggered dose-dependent inhibition of BBOX1 and EFEMP1." (PMID 30008265, 2018). "Additionally, large‐scale microarray data analysis showed that BBOX1 may be related to cancer, such as of the breast, cervix, kidney, and skin." (PMID 36864013, 2023). "Upon further dose- and time-dependent exosome transfection experiments validation by qRT-PCR, we found that cancer exosomes induced stronger upregulation of MMP9 and PGAM1 whilst suppressed BBOX1 and EFEMP1, compared to normal exosomes." (PMID 30008265, 2018). "Here, the volcano plot analysis sheds light on some genes, including RGS5, BBOX1, PKHD1L1, and TXRND3, that are associated with cancer." (PMID 36790468, 2023). "Our finding that BBOX1 and EFEMP1 were suppressed by cancer exosomes may indicate activation of a protective mechanism in the recipient cells against potentially harmful cargos in cancer exosomes." (PMID 30008265, 2018).
tumor (5 papers, 2016 to 2025). "In summary, this study demonstrates that low BBOX1 expression is associated with tumor necrosis, high histological grade, and shorter survival time in ccRCC." (PMID 36864013, 2023). "We investigated tumor‐infiltrating immune cells and gene sets related to BBOX1 with gene set enrichment analysis (GSEA) and pathway network analysis." (PMID 36864013, 2023). "Another study showed that genetic depletion or pharmacologic inhibition of BBOX1 restricts TNBC tumor growth in vitro and in vivo." (PMID 36864013, 2023).
kidney diseases (1 paper, 2019). "Further bioinformatics analysis also suggested that tubular BBOX1 mRNA expression was quite stable in various types of kidney diseases." (PMID 30819181, 2019).
BBOX1 also shares sentences with these, for which no sentence is quoted: cardiovascular disease (2 papers); carnitine deficiency (2); adenocarcinoma of the lung (1); anemia (1); angina (1); astrocytoma of the brain (1); cardiac hypertrophy (1); cardiomyopathy (1); chronic heart failure (1); chronic kidney disease (1); diabetic kidney disease (1); focal segmental glomerulosclerosis (1); hypertensive nephropathy (1); hyperthyroidism (1); hypothyroidism (1); IgA nephropathy (1); membranous nephropathy (1); metabolic disorders (1); non-alcoholic fatty liver disease (1); Primrose syndrome (1); renal cell carcinoma (1); viral infection (1).